AFP (alpha fetoprotein)
Diseases named in the same sentence as AFP in open-access papers (continued):
Sharing a sentence is not in itself a finding about the gene and the disease.
tumor (continued). "Applying a criteria of either AFP ≥ 20 IU/ml or MDK ≥ 0.44ng/ml, a significantly greater number (77%) of tumours would have been detected compared to 43% if AFP was used alone." (PMID 27219517, 2016). "Univariate analysis with log-rank test identified five significant prognostic factors for OS: TAE/TACE, tumor size, EQD2, BED10 and AFP ≥100 ng/mL." (PMID 27809890, 2016). "For clinical use, the ITA.LI.CA prognostic system can be synthetized in a single formula, TSFA, where TS is the tumor stage, F is point value of the ITA.LI.CA functional score, and A is the AFP point value." (PMID 27116206, 2016). "Nevertheless, there were no significance between preoperative ANRI and other clinicopathological parameters such as age, gender, AFP, tumor number, TNM, tumor differentiation and complication (all P > 0.05)." (PMID 27472390, 2016). "Eight serological tumor markers (CA19-9, CEA, CA242, CA72-4, CA50, CA125, CA153, and AFP) are routinely used in clinical practice to make diagnoses, determine prognoses and monitor therapeutic responses in gastroenterological cancers." (PMID 26745601, 2016). "Tumour size, tumour ADC, tumour-to-liver ADC ratio (ADCT/L), maximal tumour SUV and tumour-to-liver SUV ratio (SUVT/L) were measured and compared to serum alpha-fetoprotein (AFP) levels, tumour size and differentiation grade on explanted specimens." (PMID 26883745, 2016). "Immunohistochemical studies highlighted the presence of embryonal and yolk sac tumour components as evidenced by positive CD30 and AFP, respectively." (PMID 27807495, 2016). "The correlations of TIP30 expression with TNM stage, tumor differentiation, serum HBV titer, and alpha‐fetoprotein (AFP) level were evaluated." (PMID 27418384, 2016). "This down-regulation correlated with tumor vascular invasion, Edmondson–Steiner grade, TNM stage, and AFP level." (PMID 27811373, 2016). "Univariate analyses indicated HEY2, as well as tumor size, AFP, tumor capsule, TNM stage, vascular invasion, lymph node metastasis and tumor differentiation, served as a prognostic factor in HCC." (PMID 27191260, 2016). "Pre-operative tumor markers are as follows: lactate dehydrogenase (LDH) 204 IU/L [normal range 120–240 IU/L], alpha-fetoprotein (AFP) 3.3 ng/mL [normal range <7.9 ng/mL], β-human chorionic gonadotropin (β-hCG) <2 mlU/mL [normal <5 mIU/mL]." (PMID 32259162, 2016). "We found that serum CA19-9 levels were correlated with gender, age, and tumor depth, serum AFP levels were correlated with pathological type, and serum CA125 levels were correlated with gender, tumor size, pathological type, tumor depth, and LNM." (PMID 27533455, 2016). "We also found a significant correlation between NLR and several clinico-pathological characteristics: AFP, PVTT, tumor size, tumor encapsulation, recurrence, PNI and PLR." (PMID 26907597, 2016). "As noted in this study, the levels of AFP and DCP increased significantly with increasing sizes of the tumour nodules." (PMID 26341083, 2015). "Most of the current serum tumor markers are based on the antigen determination method, including CEA, AFP, hCG, PSA, and CA125, but lack tumor specificity and often cannot be used in early cancer screening and diagnosis 56–63." (PMID 25504773, 2015). "Several tumor markers for HCC, such as alpha fetoprotein (AFP), retinol-binding protein 4, desgamma-carboxy prothrombin time (DCP) and AFP-leptin 3 (AFP-L3), have been identified as potential candidates to evaluate the prognosis of patients with HCC." (PMID 25970775, 2015). "The threshold levels were set at AFP ≤ 25 ng/ml, TNM stage: I vs. stage II–II and tumor size < 3 cm." (PMID 26506518, 2015). "Laboratory tests like routine blood examinations and tumor markers (such as CA199, CEA, AFP, PSA, and CA125) are frequently within the normal range." (PMID 26166115, 2015). "The controversy was largely laid to rest when it was discovered that the sensitivity, specificity and accuracy of AFP and DCP vary according to tumour sizes." (PMID 26341083, 2015).
tumor (continued). "Both groups were well balanced for all variables, including age, sex, the maximum diameter of the tumor, number of tumors, DCP level, AFP level, and Child-Pugh classification." (PMID 25922554, 2015). "Pathologically, immunoreactivity for AFP and extramedullary hematopoiesis (EMH) within the tumor vessels are also of value." (PMID 26337640, 2015). "Among 90 patients, 8 (8.9%), 19 (21.1%), and 63 (70.0%) had an elevated level of AFP, elevated level of DCP, or elevated level of both these tumor markers, respectively." (PMID 25992784, 2015). "During a routine examination in 2008, this patient had an elevated alpha-fetoprotein (AFP, which is the specific tumor marker of HCC) level of 56 IU/ml (normal level 0 to 8 IU/ml)." (PMID 25649133, 2015). "Increased expression of A20 was negatively correlated with the tumor size, TNM stage, tumor thrombus formation, capsular invasion and serum AFP levels." (PMID 26538215, 2015). "Physical examination and all biochemical laboratory results were within normal limits, including liver function tests, tumour markers (CA19-9, CEA, AFP, and CA15-3), and chromogranin A. Abdominal ultrasound showed an 8 cm tumour in liver segment IV." (PMID 26064749, 2015). "On comparing the AFP level with tumor differentiation, 60.4% patients with well-differentiated HCC had AFP ≤20ng/ml." (PMID 26658912, 2015). "As one new tumor marker of HCC, GP73 holds the promise for early diagnosis of HCC because the sensitivity and specificity of GP73 are both superior to those of AFP." (PMID 26583119, 2015). "However, it is unknown whether the biological role of AFP is involved in regulating the metastasis factors of tumor progression, which is yet another important and interesting aspect of AFP since serum AFP level was significantly correlated with tumor progression and patient survival time." (PMID 25815363, 2015). "All laboratory parameters, including major tumor markers (carcinoembryonic antigen (CEA), carbohydrate antigen (CA) 125, CA19-9, squamous cell carcinoma antigen (SCC), and alpha-fetoprotein (AFP)), were within normal limits." (PMID 25763284, 2015). "HCC patients can be classified to different subgroups with different risks of tumor recurrence and prognosis according to Cezanne expression in HCC tissue and preoperative AFP level." (PMID 25638165, 2015). "Again, tumor size, TNM stage, Child-Pugh class and laboratory findings, such as AFP and Hs-CRP remained significant OS predictors." (PMID 25970775, 2015). "Parameters which related to liver function (DBIL, ALB, PT, INR, Child-Pugh stage), inflammatory activity in the liver (ALT, AST, γ-GGT, LDH, ALP), and tumor stage (BCLC stage, AFP) were significantly different between two groups." (PMID 25688365, 2015). "The as-prepared composites were used as electrochemical immunoprobes in simultaneous detection of four tumor biomarkers (carcinoembryonic antigen (CEA), carbohydrate antigen 19-9 (CA199), carbohydrate antigen 72-4 (CA724), and alpha fetoprotein (AFP))." (PMID 26577799, 2015). "HCC patients can be classified to different subgroups with different risks of tumor recurrence and prognosis according to Cripto-1 expression in HCC tissue and preoperative AFP level." (PMID 26375669, 2015). "Univariate analysis demonstrated that the significant prognostic factors for HCC recurrence were tumor size, tumor number, histopathological grade, PVTT, preoperative AFP level, TNM stage and PVT1 expression (all P<0.05)." (PMID 25624916, 2015). "Promoters derived from hTERT, survivin, Cox2, AFP and E2F1 gene have been used to drive tumor-specific suicide gene expression." (PMID 26571389, 2015). "Tumor marker serologies (CA19-9, CEA, and/or AFP) were performed in 17 cases and were elevated in 6 of (35.3 %, 6/17)." (PMID 26122082, 2015). "Levels of the serum markers alpha-fetoprotein (AFP) and des-gamma carboxyprothrombin (DCP) correlate with tumor recurrence post-transplant." (PMID 28943622, 2015).
tumor (continued). "Further, alpha-fetoprotein is shown in this study to be less sensitive and of inferior accuracy in the diagnosis of HCC when compared with DCP for patients presenting with tumour size ≥3 cm." (PMID 26341083, 2015). "The treatment included transsacral tumor biopsy, adjuvant chemotherapy (cisplatin, etoposide and bleomycin-PEB), and pelvic radiation and after 3 months; AFP levels declined to 2.6 ng/mL." (PMID 26504900, 2015). "The tumor markers carcinoembryonic antigen (CEA), carbohydrate antigen (CA19-9), and alpha-fetoprotein (AFP) were all within the normal range." (PMID 26585230, 2015). "Serum tumor markers such as carcinoembryonic antigen (CEA), alpha fetoprotein (AFP), and beta human chorionic gonadotropin (β-HCG) were normal." (PMID 25070647, 2014). "While, as of tumor-related factors in NBNC patients, although AFP levels were the lowest, the percentages of the patients with tumors more than 10 cm in diameter and tumors beyond Milan criteria were high, showing similar percentages to HBV patients." (PMID 24745029, 2014). "Total AFP can be separated into three glycoforms; of those the AFP-L3 glycoform, consisting of core-fucosylated AFP, has been shown to be highly specific for HCC even at early stage of disease and useful for early tumor recognition." (PMID 24689054, 2014). "Positive detection rates of tumor markers were: CA19-9 (49.3%), CA125 (45.1%), FER (44.2%), CA242 (42.5%), CEA (38.6%), CA15-3 (36.7%), β-HCG (29.6%), AFP (24.5%), NSE (18.2%), PSA (19.5%), f-PSA (9.4%) and HGH (8.7%) respectively." (PMID 25381564, 2014). "It has also been confirmed that an increased AFP level in the serum and cerebrospinal fluid correlates with the presence of a YST tumor." (PMID 25202397, 2014). "Levels of serum α-fetoprotein (AFP), carcinoembryonic antigen (CEA) and other tumor markers were normal." (PMID 24959257, 2014). "AFP and CEA are tumor markers that are present at normal levels in ~100% of patients with PHL, which assists the differential diagnosis." (PMID 24959257, 2014). "A panel of 13 established tumor markers was assessed alongside YB-1/p18 in the cohort of patients with malignancies, namely CA 125, CEA, CA 15–3, CA 19–9, CA 72–4, CYFRA 21–1, NSE, AFP, β2-microglobulin, SCC, thymidine kinase, TPA, and PGRP." (PMID 24443788, 2014). "Before chemotherapy, meticulous staging was done, including tumor markers (B-human chorionic gonadotropin (B-HCG), alpha-fetoprotein (AFP), and lactic dehydrogenase (LDH)), and abdominal and pelvic computerized tomography (CT) scans were carried out." (PMID 24498512, 2014). "The KIF18A expression level had positive relevance to the alpha-fetoprotein (AFP) (≥200 ng/ml), tumor size (≥5cm), clinical tumor-node-metastasis (TNM) stage and portal vein tumor thrombus (PVTT) in HCC (all P <0.05)." (PMID 25431949, 2014). "Results of laboratory tests including the levels of the tumor markers, including PSA, CEA, CA19-9, β-HCG, AFP, and CA125, were within the normal range." (PMID 24767516, 2014). "The other tumor arose in a 74-year-old female patient with chronic HCV hepatitis, whose serum AFP level had been markedly elevated (5285 ng/ml)." (PMID 26034695, 2014). "Trypsin samples mixed with several common tumor markers (including carbohydrate antigens CA125, CA199, CA153, and α-fetoprotein [AFP]) at concentrations 10–1000 times higher than that of trypsin were tested using a differential pulse voltamtery (DPV) assay." (PMID 24919018, 2014). "Complete blood count, serum biochemistry, and tumor markers (CA 19-9, CA-125, CEA, AFP, and NSE) were all within normal range." (PMID 25431731, 2014). "It was found that tumor burden, Child Pugh score, PVT, AFP level were independent prognostic factors of survival in Egyptian HCC cohort in this study." (PMID 24603710, 2014). "Among the upregulated genes, PGC, AFP, AKR1B10 and GPC3 showed more than 30-fold increased expression in the HCC tumor group." (PMID 25217841, 2014).
tumor (continued). "Most of the studies focus on either the prognosis of different AFP levels or the recurrence and side effects of FNA in relationship to tumor size." (PMID 25170868, 2014). "Statistical analyses showed significant correlations between pre-treatment serum AFP level (AFPT0) and recurrent tumor size (RTS) (P < 0.05) and between 3-month post-treatment AFP level (AFPT3) and RTS (P < 0.05)." (PMID 24993566, 2014). "Tumor markers including CA19-9 (carbohydrate antigen 19-9), AFP (alpha-fetoprotein), CA 125 (cancer antigen 125), and CEA (carcinoembryonic antigen) were normal." (PMID 24839445, 2014). "Pooled data from all five studies showed a significant correlation between high NLR and higher incidence of AFP ≥ 400 ng/ml (OR: 1.46, 95% CI: 1.01–2.09, P = 0.04).Five studies reported the relationship between NLR and tumor size in HCC." (PMID 24559042, 2014). "Next, we evaluated the expression of GPC3 in relation to the clinicopathological features, such as age, sex, AFP level and HBsAg or HCV in serum, HCC differentiation, tumor size, and metastasis." (PMID 24498024, 2014). "The levels of tumor markers such as PSA, carcinoembryonic antigen (CEA), beta-human chorionic gonadotrophin (β-HCG), alpha-fetoprotein (AFP), carbohydrate antigen 19–9 (CA19-9), and cancer antigen 125 (CA125) were normal." (PMID 24767516, 2014). "Marked increase in AFP was revealed at 151 days after the diagnosis of HCC, but the diameter of the tumor decreased continuously during 152 days after the diagnosis in the present case." (PMID 25431715, 2014). "Serum tumor markers including CEA, AFP, CA 12.5, CA 19.9, and NSE were within normal range while chromogranin A was moderately elevated." (PMID 24653852, 2014). "Tumor cells exhibited positivity for Hepatocyte, MOC31, CEA and CK19, and negativity for CD117 and AFP." (PMID 23599762, 2013). "In this model, we examined the CA125, CA199, CEA and AFP levels in blood and ascites, only to find that the CA125 level alone rose in the tumor-bearing mice." (PMID 23384043, 2013). "The tumor marker levels, including those of carcinoembryonic antigen (CEA), CA19-9, CA125, lactate dehydrogenase and alpha-fetoprotein (AFP) were within normal ranges." (PMID 23599742, 2013). "Tumor markers including cancer embryonic antigen (CEA), alpha fetoprotein (AFP), and carbohydrate antigen (CA) 19–9 were all within normal limits." (PMID 23533870, 2013). "The immunoprofile of the tumor was CD99 (+), calretinin (+), inhibin (+), alpha smooth muscle actin (+), vimentin (+), ER (−), PR (−), keratin AE1/AE3 (−), alpha fetoprotein (−), CD117 (−), and placental alkaline phosphatase (−)." (PMID 23762714, 2013). "Thus, AFP may be a passive tumor marker and an active tumor growth stimulator." (PMID 23382965, 2013). "With multivariate analysis, the present study revealed Child-Pugh class, tumor size, tumor multiplicity, presence of PVT, AFP, CRP and NLR as independent factors predictive of outcome of HCC." (PMID 23409924, 2013). "To investigate the in vivo expression pattern of our newly developed hCMV/AFP construct, we utilized the HUH7 xenograft tumor model in immune compromised nude mice." (PMID 23734827, 2013). "Analyzing of 196 primary HCC samples indicated that FLOT1 expression was strongly correlated with tumor size (P = 0.025), clinical stage (P<0.002), CLIP stage (P<0.001), vascular invasion (P<0.001), relapse (P<0.001), and serum AFP levels (P = 0.025)." (PMID 23840303, 2013). "Histology, Cytogenetic, immunohistochemistry,tumor markers of CA125,AFP, CA-199 and CEA were used to analyze the model." (PMID 23384043, 2013). "The overexpression of PTP4A3/PRL-3 was significantly correlated with the serum levels of AFP and PIVKA-II, tumor vascular invasion, and advanced cancer stages in HCC patients." (PMID 23064776, 2013).
tumor (continued). "This benefit of combined treatment was also confirmed through multivariate analysis after adjusting for other predictors such as Child-Pugh class, tumor size, EHS and/or RNI, alpha-fetoprotein level, and cumulative dosage of sorafenib." (PMID 24155932, 2013). "Serum levels of the tumor markers such as carcinoembryonic antigen (CEA), carbohydrate antigen 19-9 (CA 19-9), alpha fetoprotein (AFP), Ca 15-3, Ca-125, and Ca 72-4 became normal." (PMID 24251051, 2013). "In analyzing the CA125, CA199, CEA and AFP levels in serum and ascites, we found that only the CA125 level rose in both serum and ascites in the tumor-laden mice." (PMID 23384043, 2013). "To confirm the inhibitory effect of metformin on the self-renewal of tumor-initiating HCC cells, we conducted immunocytochemical analyses of the expression of EpCAM and α-fetoprotein (AFP), hepatic stem/progenitor cell markers, in the resultant spheres." (PMID 23922888, 2013). "Tumor grade (P=0.035), AJCC stage (P<0.001), serum AFP (P=0.014) and circulating Lin28B (P=0.001) were significantly associated with early recurrence less than one year in the univariate model." (PMID 24244607, 2013). "Univariate Cox regression analyses revealed that higher level of FLOT1, Tumor size, Tumor multiplicity, clinical Stage, CLIP stage, vascular invasion, relapse as well as serum AFP levels were all were worse predictors for HCC patients." (PMID 23840303, 2013). "In the 196 cases of tested HCC samples, FLOT1 protein level was positively correlated with Tumor size (P = 0.025), clinical stage (P<0.002), CLIP stage (P<0.001), vascular invasion (P<0.001), relapse (P<0.001), and serum AFP levels (P = 0.025)." (PMID 23840303, 2013). "Then, we looked at the association between survival and clinical parameters including age, etiology, the largest size of tumor, the number of lesions, serum markers such as bilirubin, creatinine, INR, CRP, albumin, and AFP." (PMID 24367506, 2013). "Serum tumour markers beta Human chorionic gonadotropin (beta HCG), alpha fetoprotein (AFP) and lactic dehydrogenase (LDH) were within normal limits." (PMID 24321309, 2013). "Conventionally, HCC prognosis has been primarily based on tumor stage and histologic grade in addition, angiolymphatic invasion (ALI) and high alpha fetoprotein (AFP) levels are known to correlate with shorter disease-free survival (DFS)." (PMID 23162604, 2012). "Because an elevated level of AFP may not be a reliable diagnostic tumor marker in the neoinfantile age period, it has been reported that the origin of AFP is distinguishable by the measurement of a different isoform of AFP, known as the lectin fraction (AFP-L3)." (PMID 22312308, 2012). "The 5-year survival was lower in patients with elevated AFP (P =0.012), CEA (P =0.000), CA19-9 (P =0.000), or CA50 (P =0.000) compared with those patients with normal levels of tumor markers." (PMID 22540862, 2012). "The significant prognostic factors included: the serum level of AFP, CEA, CA19-9, and CA50, age, tumor size, tumor site, Borrmann type, lymph node stage, nervous invasion, and lymphovascular invasion." (PMID 22540862, 2012). "Stratified survival analysis of HCC, according to clinical stage, tumor size and serum AFP, evaluated PLK4 expression to be closely correlated with survival of HCC patients with stage III–IV, larger tumor size and high-level AFP." (PMID 22829937, 2012). "Further analyses showed that LOH at 3 SNPs in HPSE was correlated with serum AFP, HBV-DNA level and tumor stage." (PMID 22952874, 2012). "Growth inhibition of the tumor and the systemic anti-tumor immune response were measured on CT26/PSA and CT26/AFP mice model." (PMID 23112956, 2012). "Alpha feto-protein (AFP), a tumor marker for hepatocarcinoma, can help interpret liver images whereas pathology can confirm the stage of the disease." (PMID 22536498, 2012).